PTH (parathyroid hormone)
Diseases named in the same sentence as PTH in open-access papers (continued):
Sharing a sentence is not in itself a finding about the gene and the disease.
chronic kidney disease (continued). "Chronic kidney disease (CKD) is frequently accompanied by CKD–mineral and bone disorder (CKD-MBD), a systemic disturbance of calcium, phosphate, parathyroid hormone, and vitamin D metabolism that progressively impairs bone strength and markedly increases fracture risk as renal function declines." (PMID 41596293, 2026). "Biochemically, patients present with low circulating levels of fibroblast growth factor 23 (FGF23) and parathyroid hormone (PTH), likely resulting (at least partly) from tubular phosphate leak and in contrast to patients with chronic kidney disease (CKD) with a different primary diagnosis." (PMID 39540998, 2024). "We evaluated the patient for chronic kidney disease mineral bone disease (CKD-MBD), which revealed an intact PTH (iPTH) level of 2500 pg/mL, an alkaline phosphatase (Alp) level of 4340 IU/L, a phosphorus (P) level of 9 mg/dL, and a calcium (Ca) concentration of 7.2 mg/dL." (PMID 39152506, 2024). "Parathyroid hormone (PTH) is involved in many metabolic diseases, such as chronic kidney disease (CKD) and calcium disorders, and its measurement could be of clinical utility." (PMID 34827832, 2021). "In non-dialysis chronic kidney disease (ND-CKD), serum levels of parathyroid hormone (PTH) progressively increase since the early stages of disease in order to preserve phosphate (P) homeostasis." (PMID 30138402, 2018). "International Guidelines for mineral bone disorders recommend that in Non Dialytic-Chronic Kidney Disease (ND-CKD) clinical decisions should be based on the trend of serum PTH changes over time rather than on a single value." (PMID 30138402, 2018). "In chronic kidney disease (CKD), hyperphosphatemia induces fibroblast growth factor-23 (FGF-23) expression that disturbs renal 1,25-dihydroxy vitamin D (1,25D) synthesis; thereby increasing parathyroid hormone (PTH) production." (PMID 30513912, 2018). "In CKD (chronic kidney disease) patients, plasma FGF23 concentration raises as early as in stage 2, which is much earlier than when the significant changes of phosphatemia or serum PTH concentration occur." (PMID 27941640, 2016). "For patients with chronic kidney disease (CKD) stage 5 who are on dialysis, the Kidney Disease: Improving Global Outcomes (KDIGO) guideline suggests maintaining intact parathyroid hormone (iPTH) values within the range of approximately two to nine times the upper normal limit." (PMID 26064934, 2015). "Effects of the DASH diet on blood pressure, phosphorus, intact parathyroid hormone, creatinine, and albuminuria were not modified by baseline eGFR (mean 84.5 ± 18.0 ml/min/1.73 m2, range 44.1 to 138.6 ml/min/1.73 m2) or the presence of chronic kidney disease (N=13%)." (PMID 26380159, 2014). "Kidney Disease: Improving Global Outcomes defines chronic kidney disease-mineral and bone disorder (CKD-MBD) as a systemic syndrome characterized by abnormalities in serum calcium, phosphorus and parathyroid hormone (PTH) concentration, vitamin D metabolism, and bone turnover." (PMID 24066946, 2013). "The cornerstone of this condition is characterized by the CKD-MBD (chronic kidney disease-mineral bone disorder) syndrome where there is secondary hyperparathyroidism (SHPT), manifested by parathyroid hyperplasia and upregulated synthesis and secretion of PTH." (PMID 23509710, 2013). "*For patients with chronic kidney disease (CKD) on hemodialysis, the target PTH range is approximately 2-9 times the upper limit of the normal range (ULN)." (PMID 39912010, 2025). "2-Methylene-19-nor-(20S)-1α-hydroxy-bishomopregnacalciferol 942 [20(S)-2MbisP] were able to suppress PTH at levels that did not stimulate bone resorption, intestinal calcium, or phosphate absorption and may have potential for use in the treatment of 2HPT in chronic kidney disease." (PMID 36432615, 2022).
chronic kidney disease (continued). "According to the Kidney Disease Outcomes Quality Initiative (KDOQI), PTX is recommended in patients with chronic kidney disease (CKD) stages 3–5, parathyroid hormone levels (PTH) beyond 800 ng/mL and no response to medical therapy." (PMID 35054103, 2022). "Chronic kidney disease-mineral and bone disorder (CKD-MBD) is characterized by one or more of the following manifestations: (i) renal osteodystrophy (ROD), (ii) vascular and soft tissue calcification, and (iii) abnormal metabolism of calcium, phosphorus, parathyroid hormone (PTH) or vitamin D." (PMID 33202788, 2020). "Aims/Introduction: Chronic kidney disease (CKD)-mineral and bone disorders (CKD-MBD) are an adverse outcome derived from decreases in kidney function, where abnormality of serum concentrations of calcium (Ca), phosphorus, parathyroid hormone (PTH), and vitamin D can be seen simultaneously." (PMID 32582730, 2020). "Nevertheless, calcium and PTH serum levels are not a useful indicator for the presence of PC in patients with THP, due to the end-stage renal disease: in fact, the kidney does not respond to parathyroid hormone in such cases." (PMID 33343947, 2020). "This study aimed to investigate parathyroid hormone (PTH) status during canine acute kidney injury (AKI); while renal secondary hyperparathyroidism (RSHPT) is known to be a consequence of chronic kidney disease (CKD), there are no data regarding PTH concentrations in AKI patients, to date." (PMID 40005891, 2025). "In early stages of chronic kidney disease (CKD), serum phosphate is normally maintained within the normal range owing to the compensatory increase in fibroblast growth factor-23 (FGF-23) and parathyroid hormone up until the estimated glomerular filtration rate (eGFR) reaching 30 mL/min/1.73 m2." (PMID 29850246, 2018).
hyperphosphatemia (535 papers, 2002 to 2026). Abnormally high level of phosphate in the blood. "Previous studies have shown that hyperphosphatemia causes an increase in parathyroid hormone (PTH), and in the general population, elevated PTH is associated with cognitive decline and an increased incidence of dementia." (PMID 39639681, 2024). "Hyperphosphatemia and the related increases in parathyroid hormone (PTH) are each independently associated with mortality in this population." (PMID 35999520, 2022). "Plasma levels of FGF-23 and PTH were higher in the groups fed with high Pi than in those fed with low Pi, as expected based on the hyperphosphatemia associated with dietary Pi overload." (PMID 36074191, 2022). "Meanwhile, a RCT of pre-dialysis CKD patients with hyperphosphatemia showed that administration of calcium acetate caused decreases in phosphate and PTH levels and increases in the calcium level." (PMID 34069053, 2021). "Our findings showed that a high-phosphate diet was associated with hyperphosphatemia, despite the increase in PTH, FGF-23 and, consequently, of the fractional excretion of phosphate." (PMID 34357974, 2021). "Other factors have been considered as CV risk factors in the early phase of CKD, such as hyperphosphataemia, parathyroid hormone (PTH), and leptin which worsen atherosclerosis, vascular calcifications, and cardiorenal prognosis." (PMID 33102575, 2020). "In detail, in patients with protein intake from 0.8 to 1.2 g/kg/day the risk of hyperphosphatemia increases significantly when levels of PTH are > 300 pg/ml (as compared to the population with PTH levels from 150 to 300 pg/ml)." (PMID 31853791, 2020). "In CKD–mineral and bone disorder, dysregulated FGF23, klotho, vitamin D, and PTH cause progressive hyperphosphatemia, hypercalcemia, and hyperparathyroidism and contribute to the increased cardiovascular risk in patients with renal failure." (PMID 32635646, 2020). "At the structural level, elevated levels of phosphate (hyperphosphatemia) and PTH have been associated with the presence of hypertrophy and fibrosis of the LV specifically." (PMID 31551803, 2019). "Adenine caused tubulointerstitial damage with severe CRI, anemia, hyperphosphatemia, 1.8-fold increase in urinary calcium excretion, and 3.5-fold and 18-fold increases in plasma creatinine and PTH, respectively." (PMID 29078759, 2017). "PTH has also been shown to increase intestinal phosphate transport in perfused duodenal loops and has been associated with hyperphosphatemia which appears to be consistent with our results." (PMID 28218647, 2017). "MI was significantly associated with hyperphosphatemia, higher cCa levels, and high intact PTH levels." (PMID 25494334, 2014). "Calcium and phosphorus metabolism (CPM) disorders are among the most common and significant complications in HPs, among which, hyperphosphatemia, elevated CPPs and abnormal intact PTH (iPTH) level are the important risk factors for cardiovascular disease." (PMID 23837063, 2013). "On the contrary, low PTH levels indirectly increase iFGF23 levels by causing hyperphosphatemia." (PMID 40142640, 2025). "Additionally, patients often present with elevated parathyroid hormone (PTH) levels, hyperphosphatemia, and a deficiency of natural inhibitors of calcification, such as fetuin-A and matrix Gla protein." (PMID 39912010, 2025). "Previous studies have suggested that SHPT is associated with hyperphosphatemia, CaSR, vitamin D receptor, fibroblast growth factor-23, down-regulation of PTH receptor expression, reduced target organ responsiveness to PTH, PTH metabolic disorders, and regulation of miRNAs." (PMID 40394480, 2025). "Moreover, hyperphosphatemia leads to compensatory elevation of fibroblast growth factor 23 and parathyroid hormone, which can cause left ventricular hypertrophy, renal anemia, and immune dysfunction." (PMID 40236452, 2025).
hyperphosphatemia (continued). "Similarly, insufficient PTH secretion causes a larger proximal tubular reabsorption of filtered P resulting in hyperphosphatemia." (PMID 36153665, 2022). "As the renal function declines, the ability of the kidneys to appropriately excrete a phosphate load is reduced leading to hyperphosphatemia, elevated parathyroid hormone (PTH), and decreased calcitriol with the associated elevations in the levels of fibroblast growth factor-23 (FGF-23)." (PMID 34722580, 2021). "Hence, FGF23 elevation is caused by high levels of PTH or 1,25(OH)2D3, as well as hyperphosphatemia and hypercalcemia, but the mechanisms of molecular regulation and time effects are not clear." (PMID 34360805, 2021). "PTH secretion is also stimulated by an increase in extracellular phosphate, but the stimulation of 1,25(OH)2D synthesis associated with a rise in PTH limits the capacity of PTH to deal with hyperphosphatemia." (PMID 34950827, 2021). "Clinical and experimental studies have shown that hyperphosphataemia was associated with increased risk fracture in general population and significant reduction in bone strength in normal rats, likely facilitated by increases in PTH." (PMID 34836090, 2021). "Protein intake being equal, for example, the risk of hyperphosphatemia increases with PTH levels." (PMID 31853791, 2020). "In patients with CKD, common complications include hyperphosphatemia and secondary renal hyperparathyroidism (rHPT), in which disturbances in the homeostasis of calcium, phosphate, and vitamin D lead to elevated parathyroid hormone (PTH) levels and bone loss." (PMID 29394885, 2018). "In conclusion, this study showed that hyperphosphatemia, higher calcium, and high intact PTH levels were significantly associated with incident MI and that high intact PTH levels were significantly associated with incident hemorrhagic stroke in hemodialysis patients." (PMID 25494334, 2014). "Hyperphosphatemia, higher calcium, and high intact PTH levels were associated with incident MI." (PMID 25494334, 2014). "Likewise, admission in hospital would have been increased in association with hyperphosphatemia, high serum calcium level, and markedly increased serum PTH levels even in community-based sample of individuals without baseline CKD." (PMID 24719817, 2014). "In bivariate analysis, risk factors for hyperphosphatemia included higher levels of albumin (p < 0.01), higher vitamin D (p = 0.01), lower parathyroid hormone (p = 0.02), higher corrected calcium (< 0.01), lower fasting glucose (< 0.01) and lower hemoglobin levels (p = 0.03)." (PMID 23965134, 2013). "Excessive PTH secretion associated with the reduction in serum 1,25(OH)2D3 and subsequent decrease in intestinal calcium absorption, as well as with low concentration of calcitriol and hyperphosphatemia leads to the mobilization of calcium from the bone and osteitis fibrosa." (PMID 34208727, 2021). "Laboratory evaluation revealed inappropriately low PTH levels with concomitant hyperphosphatemia, consistent with hypoparathyroidism (HypoPT)." (PMID 42267299, 2026). "Laboratory findings revealed persistent hyperphosphatemia (8.8 mg/dL), elevated parathyroid hormone levels (901 pg/mL), and low vitamin D levels (9 ng/mL), indicating significant disturbances to mineral metabolism." (PMID 39982237, 2025). "Imaging revealed periarticular calcifications, and laboratory tests confirmed hyperphosphatemia with normal calcium and parathyroid hormone levels." (PMID 40524990, 2025). "Instead, it leads to hypercalciuria and hyperphosphatemia because it lacks renal calcium reabsorption and phosphaturia typically stimulated by PTH." (PMID 40177730, 2025). "Laboratory evaluation revealed normocytic normochromic anemia, hyperphosphatemia, normal serum calcium levels, and elevated parathyroid hormone (PTH)." (PMID 40546520, 2025).
hyperphosphatemia (continued). "In that study, phosphate overload induced hyperphosphatemia and changes in bone microarchitecture, but it notably highlighted the importance of adjusting PTH levels." (PMID 40573160, 2025). "Controlling hyperphosphatemia inhibits PTH secretion in CKD patients with mild to moderate disease as well." (PMID 40177730, 2025). "When using the Enrichr MGI Mammalian Phenotype 2017 database, DMRs were identified to be involved in calcium–phosphate metabolism, elevated circulating parathyroid hormone levels, hyperphosphataemia, and retinitis pigmentosa." (PMID 39882510, 2025). "Laboratory findings are low PTH, low alkaline phosphatase, low-normal calcium, and sustained hyperphosphatemia." (PMID 41473615, 2025). "Laboratory tests showed persistently elevated serum creatinine levels, hyperphosphatemia, anemia, increased PTH levels and Grade 2 parenchymal echogenicity on ultrasound kidney, ureter, bladder (KUB) indicative of CKD." (PMID 40922257, 2025). "In advanced stages of CKD, PTH becomes insufficient to facilitate adequate renal phosphate excretion, culminating in a biochemical profile characterized by hypocalcemia, hyperphosphatemia, and decreased levels of active vitamin D." (PMID 41140700, 2025). "Phosphate binders can correct hyperphosphatemia to maintain normal serum calcium and PTH levels, and are categorized into calcium-containing (calcium carbonate) and calcium-free (sevelamer) phosphate binders." (PMID 40510469, 2025). "This supports the established pathophysiology, whereby prolonged exposure to hyperphosphatemia, reduced calcitriol synthesis, and parathyroid hyperplasia drive persistent elevations in PTH." (PMID 41492600, 2025). "This conclusion was based on the combination of hyperphosphatemia, suppressed parathyroid hormone, suppressed 25‐hydroxyvitamin D level, and a calcitriol level at the high end of the reference interval." (PMID 41356631, 2025). "Its secretion is stimulated by high phosphate intake, hyperphosphatemia, 1,25-dihydroxyvitamin D (1,25(OH)2D), and parathyroid hormone (PTH)." (PMID 37991698, 2024). "It states that the decline in kidney function in CKD leads to hyperphosphatemia, which in turn stimulates the release of PTH to enhance phosphate excretion." (PMID 39364464, 2024). "In mice and rats, short-term application of such inhibitors reduces hyperphosphataemia, PTH and FGF23 and ameliorates vascular calcification." (PMID 37660247, 2024). "Hyperphosphatemia (p < 0.001), increased parathyroid hormone (p < 0.01) and triglyceride levels (p < 0.01), hypoalbuminemia (p < 0.01) and decreased hemoglobin values (p < 0.001) in the CUA cohort were significantly different from those in the NUC group." (PMID 38178572, 2024). "External pulse-administration of PTH mimics the intermittent PTH profile in an attempt to rescue the anabolic bone status and to reduce hyperphosphatemia." (PMID 38785509, 2024). "At early stages, CKD results in defective vitamin D activation in the kidney, resulting in hypocalcemia and hyperphosphatemia and a compensatory increase in parathyroid cells and PTH secretion, leading to SHPT." (PMID 37904427, 2023). "Second, we used inorganic phosphorus and PTH levels as indicators of physiological changes in CKD, however, the change in fibroblast growth factor 23 (FGF-23) level precedes hyperphosphatemia and is observed concurrently with PTH level elevation." (PMID 36890290, 2023). "On the other hand, increased skeletal resistance to PTH results in osteodystrophy in CKD, and continued development of SHPT leads to hyperphosphatemia, vascular and organ calcification, and an increased risk of all-cause mortality." (PMID 37051200, 2023). "Their study revealed that a nursing education program was effective in decreasing phosphate levels and itching of hyperphosphatemia patients, but it was inconsistent regarding the impact of education on phosphorous, PTH and calcium levels." (PMID 37448728, 2023).